IL1B (interleukin 1 beta)
Diseases named in the same sentence as IL1B in open-access papers (continued):
Sharing a sentence is not in itself a finding about the gene and the disease.
Sepsis (continued). "Renal and pulmonary expression of NLRP3 and Caspase 1 were unchanged in response to sepsis, although tissue levels of inflammasome-associated cytokines IL-1β and IL-18 did increase in after CLP." (PMID 32555710, 2020). "IL-1β and IL-18 induce a cascade of inflammatory responses during sepsis, leading to extensive inflammatory-associated damage and multi-organ dysfunctions." (PMID 33324236, 2020). "According to previous reports, the dysregulated expression of the cytokines, IL-6, TNF-α, and IL-1β, is associated with mortality in patients with sepsis." (PMID 31333903, 2019). "Regarding inflammation, lnc‐THRIL was positively associated with CRP, PCT, TNF‐α, and IL‐1β levels in sepsis patients." (PMID 31257645, 2019). "Resveratrol treatment has also been shown to upregulate the expression of Sirt1, and IL-1β has been shown to be a proximal mediator of the inflammatory events associated with infection, sepsis, and ischemia." (PMID 30691208, 2019). "The therapeutic effects of VU0155069 on sepsis are associated with decreased production of IL-1β, and VU0155069 strongly inhibited inflammasome activation and subsequent IL-1β production from BMDMs." (PMID 31586128, 2019). "Intriguingly, a recent study has implicated macrophage FXR signaling as a negative regulator in LPS-mediated IL-1β production in sepsis-associated cholestasis." (PMID 29643332, 2018). "For instance, increased levels of IL-1β are correlated with cognitive deficits in sepsis-associated encephalopathy and a repeated social defeat model." (PMID 30319390, 2018). "Sepsis is associated with an increase in renal IL‐1β and tubular cell P2X7 expression by 6 h and 24 h, respectively." (PMID 29488356, 2018). "On the other hand, males present predominantly Th1 responses and overproduce tumor necrosis factor α (TNF-Uα), IL-1β, IL-2, IL-6, and IL-8, which in turn are frequently associated with inappropriate outcomes such as sepsis and bacteremia." (PMID 29925409, 2018). "The meta-analysis showed that genetic polymorphisms of IL-1β is associated with sepsis susceptibility." (PMID 28367457, 2017). "We suggest that Nlrp3-mediated IL-1β activation in sepsis is a major pathogenic mechanism in inflammatory muscle atrophy." (PMID 28097512, 2017). "NO and overexpressed cytokines, such as tumor necrosis factor-α (TNF-α), interleukin-1β (IL-1β), and IL-6, were also shown to cause sepsis-related systemic inflammation and myocardial depression in sepsis and septic shock." (PMID 29211014, 2017). "Higher synovial IL-1β concentrations were associated with clinical parameters indicating a higher disease severity (p < 0.03) excluding the incidence of sepsis." (PMID 27688601, 2016). "Widely used stimuli include lipopolysaccharides (LPS), which activate the TLR pathway primarily through the TLR4 receptor, and cytokines implicated in sepsis, such as interleukin 1β (IL-1β)." (PMID 26790027, 2016). "Although the pathophysiological mechanisms underlying sepsis are unclear, pro-inflammatory cytokines such as IL-6 and IL-1β, which are involved in the immune response, are clearly closely linked to the pathogenesis of sepsis." (PMID 25888255, 2015). "Seven studies totaling 745 cases and 750 controls were identified in order to investigate the association between IL-1B-511 polymorphism (rs16944) and sepsis risk." (PMID 24428862, 2014). "Susceptibility to sepsis in our study population was related to SNPs in the IL1β, MMP-16, BPI, and DEFβ1 genes." (PMID 25000179, 2014). "In the overall comparison, the IL-1B + 3594 polymorphism was significantly associated with sepsis risk in the recessive effect (OR = 0.59, 95% CI = 0.36-0.97, P = 0.04, PFDR = 0.12)." (PMID 24428862, 2014). "For example, interleukin (IL)-1β is highly relevant to the development of sepsis-associated brain dysfunction, and even in the physiologic process of cognition." (PMID 24886875, 2014).
Sepsis (continued). "Six studies containing 680 cases and 998 controls were identified that evaluated the association between the IL-1B + 3594 polymorphism (rs143634) and sepsis risk." (PMID 24428862, 2014). "On the other hand, proinflammatory cytokines, such as TNF-α and IL-1β, have been implicated in ventricular dysfunction associated with sepsis." (PMID 24371817, 2013). "Overproduction of TNF-α and IL-1β leads to tissue damage, multiple organ failure, and finally causes lethal sepsis." (PMID 24260470, 2013). "In a recent study performed in rats with polymicrobial sepsis, treatment with hyperoncotic albumin attenuates hepatic injury in association with reduced plasma levels of IL-1β, IL-6, liver enzymes, and O2- concentrations." (PMID 23548047, 2013). "Pro-inflammatory mediators, including TNF-α and IL-1β have been implicated in the pathogenesis of myocardial dysfunction and cardiomyocyte death in ischemia-reperfusion injury, sepsis, chronic heart failure, viral myocarditis, and cardiac allograft rejection." (PMID 24287918, 2013). "The effect of C5L2 during sepsis was linked to its regulation of both inflammatory cytokines (IL-1β, MIP-2, and MIP-1α) and plasma high mobility globulin β1 (HMGB1) in the blood." (PMID 23233853, 2012). "The increased concentrations of IL-1β, IL-6, IL-8, and G-CSF 7 days after combined injury were caused by the combined injury-induced sepsis due to the bacterial entry from the broken GI barrier and the skin-wound site." (PMID 22686656, 2012). "These analyses revealed that elevated sIL-2R serum levels were independently associated with severe sepsis and, furthermore that sIL-2R but also IL-1β and IL-8, were independently associated with septic shock." (PMID 22220196, 2011). "Multivariate analysis revealed independent association between sIL-2R (p = 0.01) and severe sepsis, as well as between sIL-2R (p = 0.04), IL-1β (p = 0.046), IL-8 (p = 0.02) and septic shock." (PMID 22220196, 2011). "Although IL-6 has been implicated in the triggering process of sepsis and correlates with its severity, IL-1β has been associated with the degree of VILI." (PMID 20546573, 2010). "For example, elevated levels of IL-1β and IL-18 have been linked to the pathology of sepsis and endotoxic shock, and inhibition of these cytokines has been proposed as a potential therapeutic approach." (PMID 19740426, 2009). "Therefore, this evidence indicates a role for myeloid cells (IL1B+ macrophages or CD14+ monocytes) as a shared cellular associated with the progression of Sepsis and IBD." (PMID 39993996, 2025). "Specifically, we have demonstrated that LBT exerts significant reductions in TNF-α, IL-6, and IL-1β levels while mitigating LPS-induced sepsis through the inhibition of genes associated with bacterial infection, cellular response to lipopolysaccharide, and cytokine-cytokine receptor interaction." (PMID 38799158, 2024). "For example, TNF-α and IL-1β are typically associated with the early, hyperinflammatory phase of sepsis, while IL-17 may be more involved in the later, immunosuppressive phase." (PMID 39205680, 2024). "Synthesizing previously study results with the findings of this study, rs17525809 (T253C) may be protective in severe infections such as pneumonia and early sepsis inflammasome associated illness by attenuating cytokine levels such as IL-1β and IL-18." (PMID 38966639, 2024). "Elevated circulating levels of cytokines such as TNF-α, IL-1β, IL-6, IL-8, and IL-10 have been linked to increased morbidity and mortality in patients with sepsis, suggesting that their removal could be beneficial for treatment." (PMID 39766623, 2024). "Mutations in cytosine (C) to thymine (T) at site 3954 of IL-1β exon 5 may be associated with sepsis, but there are also contrary opinions." (PMID 38848433, 2024). "In addition, IL-1β induced AChE mRNA expression in vivo and activity in vitro, reflecting the pro-inflammatory scenario caused by sepsis." (PMID 37153798, 2023).
Sepsis (continued). "In addition, studies had shown that high levels of IL-1β in the body were associated with sepsis, the IL-1β levels in the dead were higher than that of survivors." (PMID 38076268, 2023). "Herein, we hypothesized that sustained elevated IL-1β activated necroptosis to cause neuron loss, which finally led to long-term cognitive dysfunction in a neonatal rat sepsis model." (PMID 37834141, 2023). "In a previous publication, we showed that stefin B-deficient mice were significantly more sensitive to sepsis induced by lipopolysaccharide (LPS) and secreted higher levels of IL-1β due to increased inflammasome activation in bone marrow-derived macrophages (BMDMs)." (PMID 38067160, 2023). "Together, these data show that BPOZ-2 deficiency results in a greater susceptibility to sepsis, which may be partly due to the increase in serum IL-1β levels." (PMID 36936774, 2023). "In addition, IL-10 levels are important because of the role of the anti-inflammatory IL-10 by inhibiting the expression of pro-inflammatory mediators such as TNF-α and IL-1β, and by conferring diminished resistance to pathogenic organisms during sepsis." (PMID 38235139, 2023). "In addition, an increased number of neutrophils in the lungs and increased levels of pro-inflammatory cytokines such as IL-1β and TNFα in the serum is commonly observed during sepsis and, is associated with cardiac failure and death." (PMID 37624851, 2023). "We speculated that the high expression of proinflammatory cytokines (Il1β, Il6, Il8, and Tnf-α) in lung might be the main cause of respiratory inflammation and septicemia." (PMID 36447208, 2022). "In a polymicrobial sepsis model, sNASP-mutant mice had defective bacterial clearance from the lungs due to marked reductions in IL-1β, TNF-α, and IFN-γ production associated with poor adhesion molecule expression and leukocyte recruitment, and defective phagolysosome formation." (PMID 35386914, 2022). "An in vivo model has shown that inflammatory factors such as lipopolysaccharide (LPS), tumor necrosis factor-alpha (TNF-α), and interleukin-1beta (IL-1β) are associated with sepsis and could activate CMV immediate early genes and promote viral replication." (PMID 36241980, 2022). "Four cytokines, TNF-α, IL-1β, IL-6, and IL-8 have been most strongly associated with sepsis." (PMID 35563475, 2022). "The inhibition of IL-1β production by LG in rats with sepsis-associated lung injury may be associated with a decrease of serine levels in macrophages; however, this needs to be confirmed in additional in vitro studies." (PMID 36188538, 2022). "Also, the reduction in abundance of IL‐1β has been observed to play a role in the suppression of inflammation associated with sepsis in mice." (PMID 33369167, 2021). "Generally, studies to date show that IL-1b is elevated in the serum of some patients with sepsis and that initial concentrations may be associated with disease severity, but not with mortality." (PMID 33917002, 2021). "Previously noted, TXNIP exhibit a protective negative regulatory role on NO production, induction of iNOS expression as well as on NF-κB activation, while in TXNIP-deficient mice, increased sepsis susceptibility proceed despite reduced IL-1β processing by S-nitrosylation of NLRP3." (PMID 34824200, 2021). "One of the major cytokines implicated in the cytokine cascade of sepsis is IL-1β." (PMID 33101273, 2020). "Lnc‐MALAT1 was positively correlated with Scr (r = .254, P < .001), CRP (r = .494, P < .001), TNF‐α (r = .387, P < .001), IL‐1β (r = .330, P < .001), IL‐6 (r = .431, P < .001), and IL‐8 (r = .420, P < .001), while negatively associated with albumin (r = −.153, P = .033) in sepsis patients." (PMID 32309886, 2020). "In addition, IL-1β secreted by activated microglia mediated a transient synaptic deficit associated with memory impairments induced by sepsis." (PMID 33061831, 2020).
Sepsis (continued). "Prior studies of polymicrobial sepsis have shown that under conditions of Zn deficiency, the inability to supress NF-κβ activation leads to overproduction of the pro-inflammatory cytokines IL-1β and IL-6, resulting in septic shock." (PMID 31437249, 2019). "Sepsis-induced organ damage is caused by an aberrant increase in inflammatory mediators, e.g., nitric oxide (NO), pro-inflammatory cytokines (e.g., interleukin (IL)-1β and tumor necrosis factor (TNF)-α), and glutamate." (PMID 31847346, 2019). "Recent data have suggested that stimulation of primed macrophages with purified M proteins may promote inflammasome activation and secretion of IL-1β, which together with IL-6 and TNFα is implicated as a key mediator of sepsis." (PMID 29579113, 2018). "The activation of macrophages by the stimulation of the TLR4 ligand leads to the production of several inflammatory mediators, including TNF, IL-1β and IL-6, that contribute to the inflammatory response to defend pathogenic infection, but also associate with the severity of sepsis." (PMID 28593998, 2017). "Dysregulated release of IL-1β is directly associated with the development and pathogenesis of various inflammation-mediated diseases, including arthritis, Alzheimer′s disease, allergies, and sepsis." (PMID 28617316, 2017). "Because IL-1β treatment leads to decreased Myh2, Myh4, and Myh7 expression in myocytes, reduced muscular MyHC expression during sepsis might be caused by IL-1β." (PMID 28097512, 2017). "We determined the plasma concentrations of TNF-α, IL-6 and IL-1β to determine whether MCP-1 gene polymorphisms had any effect on the production of these related cytokines in the sepsis and control groups." (PMID 28472164, 2017). "TNF-α and IL-1β are major mediators causing myocardial dysfunction in sepsis." (PMID 28270914, 2017). "Sepsis resulted in cognitive impairments, which was accompanied by selective phenotype loss of PV interneurons and increased gp91phox, 4-hydroxynonenal, malondialdehyde, IL-1β, and IL-6 expressions." (PMID 26416717, 2015). "For IL-1B + 3594 (rs143634) polymorphism, genotype TT decreased sepsis risk in overall analysis (OR = 0.59, 95% CI = 0.36-0.97, P = 0.04), as well as in Caucasian (OR = 0.57, 95% CI = 0.34-0.95, P = 0.03) and sepsis (OR = 0.55, 95% CI = 0.31-0.97, P = 0.04) subgroup analysis." (PMID 24428862, 2014). "IL-1β is a prototypical proinflammatory cytokine, which stimulates both local and systemic inflammatory/immune responses, and acts synergistically with other cytokines to cause tissue injury in sepsis." (PMID 24454930, 2014). "IL-1β is an integral end-product of the inflammasome and may play an important role in sepsis-associated brain dysfunction." (PMID 24886875, 2014). "Watanabe et showed that IL-1β (−511) was associated with worsened systemic inflammation in sepsis." (PMID 24718616, 2014). "IL-1β is associated with both illness severity and mortality in human sepsis." (PMID 24886875, 2014). "The results of our meta-analysis revealed that individuals with variant genotype (TT) were less susceptible to sepsis than individuals with CC or CT genotypes in overall comparison and Caucasian population, which was inconsistent with higher IL-1β levels associated with increased risk of sepsis." (PMID 24428862, 2014). "We have demonstrated that the rs2027432 and rs12048215 polymorphisms affect IL-1β production and might be used to estimate risk for sepsis and MODS in trauma patients." (PMID 22112657, 2011). "Blood neutrophils are augmented by IL-1β and induce the overproduction of neutrophil extracellular traps (NETs), which can cause thrombus formation, epithelial and endothelial cell destruction, worsening of sepsis and ARDS, and ultimately multiple organ failure." (PMID 38474725, 2024).
Sepsis (continued). "In addition, CD38 deficiency could up-regulate ERK1/2 and NF-κB pathways in sepsis mice, accompanied by the expression of inflammatory cytokines IL-1β and chemokine MCP-1 in the lung tissues, resulting in increased pathological injury in septic lung tissues." (PMID 36998049, 2023). "During sepsis, the pathogen-associated molecular patterns trigger systemic inflammatory responses, leading to an excess production of proinflammatory cytokines that are responsible for coagulopathy, such as interleukin IL-1β, IL-6, and tumor necrosis factor-α (TNF-α)." (PMID 37219401, 2023). "Furthermore, a causative role for IL-1β has been shown in clinical trials using recombinant IL-1 receptor antagonists to inhibit IL-1 signaling, effectively reducing mortality from 65 to 35% in patients with sepsis and HBD + DIC." (PMID 35190900, 2022). "In fact, we previously reported that long-term potentiation (LTP) in the mouse hippocampus, which could be regarded as the cellular basis of learning and memory, was impaired via mechanisms associated with microglial activation and interleukin (IL)-1β activity during the acute phase of sepsis." (PMID 33643027, 2021). "However, if IL-1β directly causes muscle atrophy in sepsis and if inhibition of IL-1β prevents this response is unknown." (PMID 28097512, 2017). "Since not only sepsis is associated with inflammation-induced muscle failure and increased IL-1β levels other forms of muscle atrophy might also profit from Nlrp3/IL-1β inhibition; for example, in patients with rheumatoid arthritis and inflammatory bowel disease." (PMID 28097512, 2017). "Among the pro-inflammatory cytokines, tumor necrosis factor alpha (TNFα) and interleukin 1beta (IL-1β) are detected in the blood of patients with sepsis and are known to induce septic shock-like conditions when administered to animals in vivo, thus suggesting their key pathogenic roles in sepsis." (PMID 29259697, 2016). "Considering that sepsis is a multifactorial trait and the impact of the inflammatory cytokine on sepsis progress may be modulated by other environmental and genetic factors, more studies should be conducted to clarify the role of IL-1B + 3594 polymorphism in the etiology of sepsis." (PMID 24428862, 2014). "Notably, the reduced expression of IL-1β by MAT.Ang-1 may account for the beneficial action on blood flow and tissue perfusion in endotoxemia, as IL-1β induces neutrophil migration into tissue, causing microvascular stasis in sepsis." (PMID 23036162, 2012). "However, anti-IL-1β therapy has proved to be ineffective in sepsis trials, and inhibition of caspase-1 has been suggested as potentially rendering individuals more susceptible to infections and severe sepsis." (PMID 19740426, 2009). "In a murine model of polymicrobial sepsis induced by cecal ligation and puncture, systemic lactate administration exacerbated inflammation, increased IL-1β levels and neutrophil infiltration, induced hypothermia, and worsened survival." (PMID 41932879, 2026). "Serum levels of TLR2, TLR4, TLR9, IL-1β, IL-6, IL-8, IL-10, TNF-α and IFN-γ were quantified by enzyme-linked immunosorbent assay at the time of sepsis diagnosis." (PMID 41846925, 2026). "For example, the caspase-1 inhibitor AC-YVAD-CMK suppresses NOD-like receptor protein 1 (NLRP1) inflammasome activation and decreases IL-1β and IL-18 expression, alleviating sepsis-induced AKI in mice." (PMID 41521316, 2026). "LPS-treated mice in the sepsis/induction model group had considerably greater expression of IL-1β and TNF-α within kidney tissues than untreated controls." (PMID 41585603, 2026). "Sepsis is initiated by the host immune response and excessive inflammation, leading to the release of pro‐inflammatory cytokines such as IL‐1β, IL‐6, and TNF‐α." (PMID 41551210, 2026).